RNU1-17P (RNA, U1 small nuclear 17, pseudogene)
Gene: Small nuclear RNA gene on chromosome 5 (180,729,586 to 180,729,737, forward strand). Ensembl gene ENSG00000199892.
Homologues: Orthologues: chimpanzee U1 (86% identical), guinea pig U1 (77% identical). Paralogues in human: RNU1-1 (85% identical), RNU1-2 (85% identical), RNU1-27P (85% identical), RNU1-28P (85% identical), RNU1-3 (85% identical), RNU1-4 (85% identical), RNVU1-18 (85% identical), RNVU1-29 (85% identical), U1 (85% identical), RNU1-39P (84% identical), RNU1-89P (84% identical), RNVU1-28 (84% identical), and 134 more.